CAT (catalase)
Diseases named in the same sentence as CAT in open-access papers (continued):
Sharing a sentence is not in itself a finding about the gene and the disease.
COVID-19 (continued). "It was shown that the IgGs of patients who recovered from COVID-19 had statistically significantly higher catalase activity than those of healthy donors (1.8-fold), patients vaccinated with Sputnik V (1.4-fold), and patients vaccinated after COVID-19 (2.1-fold)." (PMID 37373231, 2023). "An increase in the catalase activity of IgG in those who recovered from COVID-19 may indicate the important role of abzymes with oxidoreductase activities in regulating the level of reactive oxygen species." (PMID 37373231, 2023). "Nanoceria, which has catalase enzyme activity, could be used for anti-COVID-19 to disrupt MAPK kinase signaling." (PMID 35995784, 2022). "Moreover, some genes related to protein secretion and reactive oxygen species pathways like MAPK1, RAB14, RAB22A, SOD1, and CAT were dysregulated in COVID-19 versus other-viral diseases." (PMID 35922752, 2022). "However, studies found decreased levels of CAT in the placentas of pregnant COVID-19 female patients and reduced SOD in the seminal fluid of COVID-19 male patients." (PMID 36009328, 2022). "Moreover, the expression of ICAM1, NOS2, and CAT was increased in CHOL/COVID-19, while the survival rate was low, although these genes were only marginally increased." (PMID 34176789, 2021). "First, we sought to investigate the systemic oxidative response in plasma obtained from our cohort of COVID-19 patients by measuring the levels of ferritin heavy chain, catalase, total superoxide dismutase (SOD) activity, total antioxidant status, iron and lipid peroxidation." (PMID 35095880, 2021). "In this work, the relative catalase activity of the serum IgGs of patients recovered from COVID-19, healthy volunteers vaccinated with Sputnik V, vaccinated with Sputnik V after recovering from COVID-19, and conditionally healthy donors were analyzed for the first time." (PMID 37373231, 2023). "In this work, we analyzed the catalase activity of the IgGs of blood plasma from patients in three groups, those recovered from COVID-19, healthy people vaccinated with Sputnik V, and vaccinated patients who had recovered from COVID-19, and compared it with conditionally healthy donors." (PMID 37373231, 2023). "Serum from patients with severe COVID-19 significantly upregulated genes involved in the cellular antioxidant response in HUVEC, including NFE2L2, HMOX1, SOD1, CAT, GPX1, and GSR." (PMID 41583455, 2025). "Virus-induced ROS production can lead to decreased glutathione (GSH) levels and activation of the antioxidant defense system including catalase (CAT) and superoxide dismutase (SOD1), as seen in COVID-19 patients." (PMID 40519923, 2025). "While total antioxidant capacity (ABTS and FRAP) was reduced in COVID-19 patients, antioxidant enzymes (SOD and CAT) and oxidative cell damage (carbonyl and lipid peroxidation (LPO)) were significantly higher in these individuals." (PMID 40867576, 2025). "Our synthesized results revealed significantly higher levels of pro-oxidants (H2O2 and TOS) and lower levels of antioxidants (SOD, CAT, GSH, thiols, and NO) in severe cases of COVID-19 compared to controls and mild cases." (PMID 41328243, 2025). "Vaccination significantly increased placental CAT and SOD1 expression and activity in COVID-19-positive women, suggesting enhanced antioxidant defense." (PMID 39768279, 2024). "For the first time, we also demonstrated that SARS-CoV-2 vaccination significantly increased the antioxidant enzymes CAT and SOD1 in the placentae of COVID-19-positive patients, eliciting a boost in placental protection against OxS." (PMID 39768279, 2024). "The expression levels of Nrf2, CAT, SOD1, and SOD2 were increased in COVID-19 patients compared to healthy subjects." (PMID 36493512, 2023). "The activity of extracellular enzymes CAT and SOD, and the total oxidant status (TOS) level were increased in plasma samples of COVID-19 patients." (PMID 36493512, 2023).
COVID-19 (continued). "AMP, along with the daily practice of SKY, during normal life (pre-COVID-19 phase) reduced mRNA expression of IL1β, IL6, and TNF and increased mRNA expression of SOD, catalase, and GPx." (PMID 37546047, 2023). "Remarkably, the results indicated decreased expression of Nrf2, CAT, SOD1, and SOD2 (P-value <0.02) as well as GP91PHOX (P-value <0.02) in COVID-19 patients compared to controls." (PMID 36493512, 2023). "Similar to our study, their study showed that serum MDA and TOS levels, and CAT and GPX activities were significantly increased in COVID-19 patients." (PMID 37112613, 2023). "The catalase activity of anti-S-IgGs and anti-RBD-IgGs in patients who recovered from COVID-19 and/or were vaccinated with Sputnik V was close to zero." (PMID 37373231, 2023). "Secondly, the COVID-19-IgGmix preparation was separated with SDS-PAGE; then, the proteins were extracted from the gel fragments, and the catalase activity of the fractions was determined." (PMID 37373231, 2023). "In contrast, we demonstrated a statistically significant increase in CAT and SOD enzymatic activity in the placenta from COVID-19 women compared to the controls." (PMID 35327436, 2022). "Meanwhile, the levels of erythrocytes glutathione (GSH), glutathione peroxidase (GPx), catalase, and plasma superoxide dismutase (SOD) are observed to be lower in COVID-19 patients when compared with those of controls." (PMID 35200677, 2022). "Increased DNA oxidative damage and significantly decreased activity of antioxidant enzymes CAT and glutathione synthetase (GSS) were found in placentas of asymptomatic and symptomatic pregnant COVID-19 female patients compared to healthy controls." (PMID 36009328, 2022). "This meta–analysis revealed significantly higher levels of pro-oxidants (H2O2 and TOS) and lower levels of antioxidants (SOD, CAT, GSH, and thiols) in severe cases of COVID-19 compared to controls and mild cases, indicating that oxidative stress contributes to the severity of the disease." (PMID 41328243, 2025). "CAT-mediated decomposition of H2O2 to water minimizes the downstream flow of excessive ROS, which otherwise could trigger OxS and m-Dys in COVID-19 and PASC patients." (PMID 38555403, 2024). "Serum levels of SOD, CAT, GSH, and GPx are significantly altered in COVID-19 patients." (PMID 38555403, 2024). "According to significant alterations in the TOS and enzyme activities of CAT and SOD in plasma samples of COVID-19 patients, the performance of these markers as discriminators of COVID-19 patients and healthy individuals was investigated by the means of logistic regression as a classifier." (PMID 36493512, 2023). "In addition to PBMCs, we thus evaluated the redox system, including CAT and SOD activities and the TOS in the plasma sample of COVID-19 patients." (PMID 36493512, 2023). "Here we introduced 1 to 3 host-based biomarker panels, including CAT and SOD enzymes and TOS metabolite that could precisely discriminate COVID-19 patients from healthy controls with an accuracy of 0.9–1." (PMID 36493512, 2023). "At the same time, the relative increase in the level of IgG catalase activity in COVID-19 patients is not high compared to others, especially autoimmune and other diseases." (PMID 37373231, 2023). "This indicates that not all anti-COVID-19 IgGs had catalase activity, and necessitate IgG subfractioning." (PMID 37373231, 2023). "Nonetheless, in our previous study, no changes were observed in either this enzyme or catalase in the semen of patients with varying DNA fragmentation indexes after COVID-19." (PMID 37958725, 2023). "Serum CAT and SOD levels were found to be lower in COVID-19 patients than in controls." (PMID 35327436, 2022). "However, despite higher CAT and SOD levels and activity reported in COVID-19 patients, the ROS levels in patients were increased and correlated with disease severity." (PMID 36009328, 2022).
COVID-19 (continued). "In this study, through network pharmacology, molecular docking, target analysis, and tissue analysis, it can be concluded that Xiyanping injection and andrographolide sulfonates such as compound III in the treatment of COVID-19 mainly act on HSP90AA1, CAT, TNF, FOS, and other targets." (PMID 35818408, 2022). "For instance, no significant changes in SOD and CAT activity in seminal plasma and spermatozoa of men after COVID-19 from groups both with normal and elevated DNA fragmentation rate were noted." (PMID 36077455, 2022). "Some studies reported no changes between the serum activities of SOD and CAT enzymes in COVID-19-infected patients, or an inhibition of antioxidant systems, leading to a decrease in the overall antioxidant capacity." (PMID 36613462, 2022). "We found a significant increase in the OxS markers TBARS (p = 0.031) and HIF-1 α (p = 0.01) and anti-oxidant CAT (gene, p = 0.039; enzymatic activity, p > 0.05) and SOD (gene, p = 0.016; enzymatic activity, p = 0.006) in the COVID-19 women compared to the CTRL group." (PMID 35327436, 2022). "Additionally, the anti-CHOL/COVID-19 effect of VA was controlled by 3 core genes, including ICAM1, NOS2, and CAT, suggesting the possible therapeutic and immunotherapeutic targets for treating COVID-19 or CHOL/ COVID-19." (PMID 34176789, 2021). "Furthermore, six core gene targets including CAT, NOS2, CXCR3, MAPK1, GPT, and ICAM1 of VA against CHOL/COVID-19 were identified using Cytoscape tool." (PMID 34176789, 2021). "Furthermore, seven core targets of VA against COVID-19, including MAPK1, IL10, EGFR, ICAM1, MAPK14, CAT, and PRKCB were identified." (PMID 32805728, 2020). "Similarly, serum levels of SOD and CAT were found to be significantly lower in non-survivors compared to COVID-19 survivors." (PMID 41328243, 2025). "CAT overexpression was accompanied by a significant increase in SOD1 mRNA levels in v-COVID-19 (p < 0.001, 3.2-fold increase; p = 0.001, 2.7-fold increase) and u-COVID-19 (p < 0.001, 2.1-fold increase; p = 0.017, 1.8-fold increase) placentae compared to the v-CTRL and u-CTRL subgroups." (PMID 39768279, 2024). "Since m-Dys and OxS jointly contribute to both COVID-19 and PASC pathology, nutritional reset of virus-induced HMRD with NAC, glutamine, GSH, and antioxidant enzymes (i.e., SOD, catalase) could potentially resolve OxS and persistent pulmonary fibrotic sequelae in PASC patients." (PMID 38555403, 2024). "Patients with COVID-19 showed a significantly higher level of pro-oxidative parameters (hydrogen peroxide (H2O2) and the index of lipid peroxidation in the form of thiobarbituric acid-reactive substances (TBARSs)) and a significantly lower activity of the antioxidant system (catalase (CAT))." (PMID 38540248, 2024). "However, vitamin C, GPx and CAT activity were not different between COVID-19 groups and controls." (PMID 37112613, 2023). "In the present study, a significant increase in CAT and SOD1 expression and activity was observed in vaccinated COVID-19-positive placentae compared to both unvaccinated and control COVID-19-negative patients." (PMID 39768279, 2024). "While we could not observe any difference of SOD, CAT and GPx activity between the two groups, the activity of GST and GR was lower in COVID-19 than No COVID-19 patients." (PMID 37408073, 2023).
prostate carcinoma (52 papers, 2006 to 2026). A carcinoma that arises from epithelial cells of the prostate gland. "A recent comprehensive metanalysis also revealed a significant correlation of CAT rs1001179 SNP with susceptibility to blood‐ and bone‐marrow‐related cancers, skin cancers, gastrointestinal‐tract‐related cancers, prostate cancer, and gynecologic cancers." (PMID 39540258, 2024). "Two meta-analyses pointed out a correlation exists between CAT rs1001179 polymorphism and prostate cancer." (PMID 36969849, 2023). "Lower expression of Cu, Zn-SOD, Mn-SOD, and catalase in intraepithelial neoplasia and prostate cancer than in benign epithelium implicated the role of oxidative stress in an early event in prostate carcinogenesis." (PMID 36290767, 2022). "Recent studies have focused on the associations of catalase polymorphisms with various types of cancer, including cervical and prostate cancers." (PMID 27449288, 2016). "A large number of previous studies in humans have suggested a possible correlation between genetic polymorphisms of CAT and susceptibility to cancers, such as prostate cancer, breast cancer, and hepatocellular carcinoma." (PMID 27449288, 2016). "Increased catalase expression has been reported in several cancer cell types, and recent meta-analyses revealed a correlation between a specific polymorphism of catalase and prostate cancer." (PMID 33287315, 2020). "CAT is located on the nuclear chromosome 11p13, and polymorphisms in this gene have been reported to associate with the development of many types of cancer, such as invasive cervical cancer and prostate cancer." (PMID 27449288, 2016). "Thus, as an example, the expression of three major antioxidant enzymes, CuZnSOD, MnSOD and catalase were altered in human prostate carcinoma which has been associated with higher sensibility to DNA damage cause by ROS." (PMID 24213319, 2012). "Also, SNPs in MnSOD, GPX1, GPX4, CAT were found to be associated with prostate cancer." (PMID 26301412, 2015). "In summary, this study demonstrates that each prostate cancer cell line exhibits unique redox characteristics and underscores the pivotal role of CAT in PCa pathogenesis by linking peroxisomal redox imbalances to cell proliferation." (PMID 39594482, 2024). "Catalase is upregulated in prostate cancer, serving to counteract the effects of hydrogen peroxide–derived oxidants." (PMID 39076107, 2024). "To further explore how variability in CAT expression among different prostate cancers affects PCa cell proliferation, we initially used 3-AT (10 mM) to inhibit CAT activity." (PMID 39594482, 2024). "In prostate cancer, changes in the activity of antioxidant enzymes (e.g., catalase, superoxide dismutase, glutathione peroxidase) and a decrease in the concentration of serum vitamins acting as antioxidants are also observed." (PMID 38774418, 2024). "The expression of antioxidant enzymes SOD1, SOD2, and catalase are lower in prostate cancer than in normal tissue." (PMID 39000269, 2024). "It has been observed that MDA and SOD levels are above the upper decision line, GSH level is below the lower decision line, and CAT level is between the decision lines in prostate cancer patients." (PMID 35720997, 2022). "Result showed that the catalase expression was significantly reduced in prostate cancer compared with normal tissues." (PMID 35488328, 2022). "We also assessed the correlation between immune infiltrates and FOXO3a and catalase expression in prostate cancer." (PMID 35488328, 2022). "In summary, our data suggested that DHT promoted cell proliferation by reducing the expression of catalase and then increasing ROS in prostate cancer cell." (PMID 35488328, 2022). "We analyzed the correlation between the expression of FOXO3a and the antioxidant enzyme catalase in prostate cancer with the TCGA and GEPIA databases." (PMID 35488328, 2022).
prostate carcinoma (continued). "The aim of the study was to analyze the activity of antioxidant enzymes (glutathione S-transferase, catalase, superoxide dismutase) and the concentration of malondialdehyde in order to determine the role of detoxification mechanisms in prostate cancer." (PMID 34409535, 2022). "DHT treatment was found to inhibit catalase activity and increase ROS level in prostate cancer cell." (PMID 35488328, 2022). "We discovered a novel mechanism by which DHT promotes prostate cancer cell proliferation via suppressing catalase activity and activating ROS signaling via a FOXO3a dependent manner." (PMID 35488328, 2022). "The high concentration of H2O2 apparently raises the activity of catalase in prostate cancer tissue." (PMID 32899343, 2020). "NAMPT is also involved in oxidative stress response as knockdown NAMPT sensitizes prostate cancer cells to H2O2 by regulating the expression of anti-oxidant genes catalase (CAT) and manganese superoxide dismutase (SOD)." (PMID 31598701, 2019). "Noticeably, elevation of SOD activity suppresses tumor growth in breast and prostate cancers, while the reduction of CAT activity triggers the intracellular hydrogen peroxide production, DNA damage, and progressing of tumor growth." (PMID 29755559, 2018). "In prostate cancer cells, ROS generation is accompanied by downregulation of antioxidant enzymes, such as manganese superoxide dismutase (MnSOD) and catalase." (PMID 27077810, 2016). "For example, downregulation of the three major antioxidants Cu/ZnSOD, MnSOD and catalase have been reported in prostate cancer." (PMID 27391159, 2016). "Results showed that the catalase expression was down-regulated in prostate cancer." (PMID 35488328, 2022). "We investigated the catalase activity in prostate cancer cell under DHT treatment." (PMID 35488328, 2022). "Based on the results of this research, we can conclude that oxidative stress which caused lipid peroxidation and protein oxidation, as well as the changes in catalase activity, might be included in prostate cancer pathogenesis." (PMID 32899343, 2020). "The stratified analysis results indicated that the CAT rs1001179 polymorphism was only associated with prostate cancer, but not other cancers." (PMID 27449288, 2016). "The cell's net redox state is a balance between oxygen radical synthesis and breakdown, and net ROS metabolism in prostate cancer arises via activities of the scavenger enzyme systems catalase, superoxide dismutase I (Zn2+/Cu2+ SOD) and II (MN-SOD), and glutathione peroxidase." (PMID 16756681, 2006). "Furthermore, it was reported that mind-body exercise could decrease the level of malondialdehyde and increase the levels of catalase, superoxide dismutase, catalase, and glutathione peroxidase in serum of prostate cancer patients." (PMID 32952591, 2020). "Some studies have reported decrease in antioxidant enzymes such as catalase, superoxide dismutase containing manganese, superoxide dismutase containing copper and zinc, glutathione peroxidase, disrupted oxidative stress / antioxidant status in prostate cancer patients." (PMID 30676303, 2019). "Along with the increased activity of GPD2 in prostate cancer cells, prostate cancer cells produce 2- to 3-fold more H2O2147 and express higher levels of antioxidant enzymes, including catalase, MnSOD, and CuZnSOD, than normal prostate epithelial cells." (PMID 38689091, 2024). "The aim of the study was to analyze the activity of antioxidant enzymes (GST, CAT, SOD) in order to determine the role of detoxification mechanisms in prostate cancer." (PMID 34409535, 2022).